HIF1A (hypoxia inducible factor 1 subunit alpha)
Diseases named in the same sentence as HIF1A in open-access papers (continued):
Sharing a sentence is not in itself a finding about the gene and the disease.
pancreatic cancer (continued). "This review mainly elucidated the major function of HIF-1α in the carcinogenesis and progression of pancreatic cancer as well as pancreas embryonic development." (PMID 32587480, 2020). "Our mechanism studies indicated that RAD51 promoted pancreatic cancer progression by enhancing aerobic glycolysis via HIF1α." (PMID 31889908, 2019). "The Cox regression analysis revealed that HIF-1α was an independent marker for evaluating the prognosis and survival of patients with pancreatic cancer." (PMID 31711497, 2019). "A large number of studies have shown that HIF-1α can be used as a marker of the survival rate of pancreatic cancer." (PMID 31711497, 2019). "Next, we examined the in vitro effect of tamoxifen treatment on the levels of HIF‐1A and the rates of proliferation and apoptosis in the pancreatic cancer cell line Suit2‐007 under hypoxic and non‐hypoxic conditions." (PMID 30538116, 2019). "Under the hypoxic condition, PAC cells are more resistant to gemcitabine-induced apoptosis than under the normoxic condition, and silencing HIF-1α of the human pancreatic cancer cell can reverse the chemotherapy drug resistance." (PMID 31886169, 2019). "When digoxigenin is used to inhibit the translation of the HIF-1α subunit, pancreatic cancer cells are more sensitive to gemcitabine." (PMID 31711497, 2019). "HIF1α protein stabilization and upregulation is regarded as an important factor in chemotherapy and radiotherapy resistance in pancreatic cancer." (PMID 31889908, 2019). "It was recently confirmed that ANXA8 induced HIF-1α transcription via calcium signaling pathways in pancreatic cancer, and can be regulated by zinc-finger transcription factor ZIC2 to inhibit apoptosis." (PMID 31474227, 2019). "Recently, HIF-1α has been reported that directly bound to the HDGF promoter region, which was highly correlated with pancreatic cancer-associated fibrosis under normoxic condition." (PMID 31711427, 2019). "At the best of our knowledge, the role of ANXA8 in calcium fluctuation-mediated HIF-1α transcriptional activation and cell viability has been studied only in pancreatic cancer." (PMID 31429720, 2019). "In pancreatic tumors, HIF-1α expression in a CD133+ stem cell-like population has been shown to promote EMT, and mutations in HIF-1α itself are key drivers of a variety of cancer types including PDA." (PMID 31666928, 2019). "Tamoxifen treatment also decreases the fitness of pancreatic cancer cells to cope with hypoxic conditions via mechanical downregulation of HIF‐1A." (PMID 30538116, 2019). "Wang et al55 used a quantitative real‐time polymerase chain reaction and IHC to investigate HIF‐1α expression in pancreatic carcinoma." (PMID 31411003, 2019). "The role of high glucose concentrations in promoting pancreatic cancer invasion involves the up-regulation of HIF-1α." (PMID 30455857, 2018). "High glucose levels can up-regulate HIF-1α expression, which promotes metastasis of pancreatic cancer." (PMID 30455857, 2018). "In pancreatic cancer, the genetic aberrations in cancer driver gene Kras were proved to regulate c-Myc and HIF1α." (PMID 29736179, 2018). "HIF-1α is the most important transcription factor induced by intratumoral hypoxia, and it predicts poor outcomes for pancreatic cancer patients." (PMID 30455857, 2018). "In this study, we assumed that hyperglycemia promotes the progress of pancreatic cancer by inducing a hypoxic microenvironment by regulating HIF-1α." (PMID 30455857, 2018). "Previous studies have revealed overexpression of HIF-1a and relevant downstream glucose metabolism genes in pancreatic cancer." (PMID 29476053, 2018). "Statistcal analysis was performed to explore the relationship between HIF-1α expression and pathological features of patients with pancreatic cancer." (PMID 30455857, 2018). "Fuco-MnO2-NPs additionally successfully reduced the HIF-1α expression in pancreatic cancer cells cultured in a hypoxic condition, indicating efficient oxygen generation." (PMID 30558324, 2018).
pancreatic cancer (continued). "In a hypoxic environment, pancreatic cancer cells express high levels of the hypoxia-inducible factor 1α (HIF-1α)." (PMID 30455857, 2018). "We also treated pancreatic cancer cells with CoCl2, a chemical which stabilizes HIF-1α, to mimic a hypoxic microenvironment." (PMID 30486896, 2018). "Another contribution of hypoxic glycolysis to pancreatic cancer malignant properties is that it participated to chemotherapy and radiotherapy resistance, by upregulating of reactive oxygen species and HIF1α." (PMID 29736179, 2018). "To explore the possible relationship between hyperglycemia and hypoxia, we examined the effects of high glucose concentrations and the expression of HIF-1α in pancreatic cancer cells." (PMID 30455857, 2018). "The expression of HIF-1α in pancreatic tumors was higher in hyperglycemic conditions than in euglycemic conditions." (PMID 30455857, 2018). "Treatment of pancreatic cancer cells under hypoxic (1%) conditions for 6–12 h significantly promoted the expression of HIF-1α, an important marker in hypoxia response." (PMID 30486896, 2018). "A recent study found that miR-142-3p is downregulated in human PDAC when compared to paired adjacent normal tissue and in pancreatic cancer cell lines, and showed that hypoxia-inducible factor (HIF1α) is a direct target of miR-142-3p in PDAC29." (PMID 29844410, 2018). "Our data showed that pancreatic cancer patients with diabetes had a higher level of HIF-1α expression as well as biliary duct invasion and larger tumor volumes than individuals in the euglycemic group." (PMID 30455857, 2018). "Promoter analysis using a HIF-specific reporter revealed that overexpression of STK33 was able to partially restore HIF-1α transcriptional activity in MIA PaCa2 pancreatic cancer cells treated with PU-H71 and incubated in hypoxic atmosphere." (PMID 29100402, 2017). "In conclusion, emodin and rhein inhibited HIF-1α expression in human pancreatic cancer cells both in vitro and in vivo." (PMID 29152137, 2017). "In the present study, emodin and rhein inhibited HIF-1α expression in MiaPaCa2 and four other pancreatic cancer cell lines in vitro and also in MiaPaCa2 cells in vivo when the cells grew as subcutaneous tumors in athymic mice." (PMID 29152137, 2017). "HIF-1α expression levels were markedly increased in all six pancreatic cancer cell lines following induction of hypoxia." (PMID 28968982, 2017). "To determine why there was accumulation of HIF-1α in pancreatic cancer cells in spite of a significant decrease in hypoxia in the tumor, we next evaluated the transcription, translation and stability of HIF-1α in these cells." (PMID 28801636, 2017). "In the current study we thus evaluated the mechanism by which Minnelide decreased hypoxia response within tumors by dampening the HIF-1α mediated pro-survival signaling and decreased the population of tumor initiating cells in pancreatic cancer." (PMID 28801636, 2017). "Using Western blotting, we demonstrated that emodin and rhein decreased HIF-1α expression in MiaPaCa2 and four other human pancreatic cancer cell lines." (PMID 29152137, 2017). "Next, SYBR green quantitative PCR analysis was performed to quantify the mRNA expressional level of HIF-1α in pancreatic cancer tissues." (PMID 28069592, 2017). "In the present study, we used them as references to assess the effects of emodin and rhein on HIF-1α expression in pancreatic cancer cells." (PMID 29152137, 2017). "For example, α-mangostin inhibits hypoxia-driven ROS-induced aggression against pancreatic cancer cells by reducing ROS production, which leads to inhibition of HIF-1α stabilization, GLI1 expression, and EMT." (PMID 28537893, 2017). "Taken together, miR-142/HIF-1α axis regulates hypoxia-induced cell proliferation and invasion of pancreatic cancer." (PMID 28069592, 2017).
pancreatic cancer (continued). "As exhibited, the expression of HIF-1α (P=0.016) and miR-142 (P=0.038) was positively or negatively correlated with the stage of pancreatic cancer, respectively, and miR-142 was negatively correlated with lymphatic metastasis (P=0.043)." (PMID 28069592, 2017). "This being the case, emodin and rhein appear to be potent HIF-1α inhibitors for pancreatic cancer cells." (PMID 29152137, 2017). "Overexpression of hif-1α correlates with lymph node metastasis and poor prognosis in patients with pancreatic cancer." (PMID 28705232, 2017). "When five human pancreatic cancer cell lines were exposed to emodin or rhein, HIF-1α was decreased dose-dependently by either reagent." (PMID 29152137, 2017). "Taken together, miR-142/HIF-1α axis was correlated with the pathological stage of pancreatic cancer, and miR-142 was correlated with lymphatic metastasis of pancreatic cancer." (PMID 28069592, 2017). "We confirmed that miR-142 inhibited pancreatic cancer cell proliferation and invasion, partly by choosing HIF-1α as its binding site." (PMID 28069592, 2017). "A HIF-1α inhibitor PX-478 attenuates pancreatic cancer cell proliferation, and it supports the effects of arsenic trioxide treatment." (PMID 29295482, 2017). "The present study demonstrated that HIF-1α expression was significantly induced in pancreatic cancer cells cultured under hypoxic condition, whereas BNIP3 expression was undetectable." (PMID 28968982, 2017). "Consistent with this, the expression of HIF-1α was found to be increased in the different pancreatic cancer cell lines at the protein level." (PMID 28801636, 2017). "In conclusion, emodin and rhein decrease pancreatic cancer cell's growth and HIF-1α expression and attenuate cancer cachexia in the athymic mice carrying the cancer cells." (PMID 29152137, 2017). "To investigate the specific role of hif-2α in pancreatic cancer, we excluded the influence of hif-1α by selectively modifying hif-2α expression." (PMID 28705232, 2017). "The expression of BNIP3 and HIF-1α proteins was investigated under normoxic and hypoxic conditions in the six pancreatic cancer cell lines." (PMID 28968982, 2017). "Our results showed that upon treatment with triptolide, HIF-1α protein accumulated in pancreatic cancer cells even though hypoxic response was decreased in them." (PMID 28801636, 2017). "Our findings demonstrate that deletion of STK33 markedly reduced hypoxia-induced accumulation of HIF-1α in colon and pancreatic cancer cells." (PMID 29100402, 2017). "We recently showed that a HIF-1α-dependent β-AR signaling pathway mediated chronic stress-induced pancreatic cancer growth." (PMID 26497365, 2016). "Our data indicate that β2-AR signaling regulates NNK enhanced pancreatic cancer proliferation and invasion via HIF-1α upregulation." (PMID 26497365, 2016). "Some studies showed that DEC2 physically interacts with and promotes HIF-1α degradation, and suppresses the malignant behaviour of human breast and pancreatic cancers." (PMID 27095063, 2016). "In the present study, we demonstrated that CD133 expression in pancreatic cancer plays a role in initiating HIF-1α expression through increasing transcriptional activity under hypoxia following encouraged tumor migration ability and EMT phenomenon." (PMID 27367674, 2016). "The transcription factor HIF1α regulates oxygen delivery and metabolic adaptation to hypoxia and has been found to be a prognostic marker for pancreatic cancer." (PMID 26774265, 2016). "In the present study, we show that smoking, HIF-1α expression and β2-adrenogenic receptor (β2-AR) expression are negatively correlated with the overall survival of pancreatic cancer patients." (PMID 26497365, 2016). "In the present study, we showed the possibility that CD133 affects HIF-1α expression and migration in pancreatic cancer." (PMID 27367674, 2016). "The effect of HIF-1α on the inflammation and fibrosis of pancreatic cancer through regulating CCL2 has been shown in the present study." (PMID 27271610, 2016).
pancreatic cancer (continued). "Our data demonstrate that PKM2 is able to regulate the NF-κB as well as the HIF-1α signaling pathways and suggest that the kinase acts upstream of these two transcription factors in pancreatic tumors." (PMID 26739387, 2016). "Our data showed that lncRNA-NUTF2P3-001 in pancreatic cancer cell was elevated under hypoxia or CoCl2, while decreased with the HIF-1α-siRNA." (PMID 26755660, 2016). "More importantly, ChIP assay and HREs luciferase reporter assay were further adopted to identify that lncRNA-NUTF2P3-001 is transcriptionally upregulated by HIF-1α in pancreatic cancer cell." (PMID 26755660, 2016). "To explore the possible role of HIF-1α and β2-AR in the triggering pancreatic cancer progression, we first explored the expression of HIF-1α and β2-AR in pancreatic cancer specimens." (PMID 26497365, 2016). "Our data indicate that β2-AR signaling mediates NNK-induced pancreatic cancer progression via upregulation of HIF-1α." (PMID 26497365, 2016). "Although, as far as we are aware, this is the first study to examine HIF1α as a downstream effector of PAK1 in pancreatic cancer, PAK1 has previously been linked to HIF1α in colorectal cancer." (PMID 26774265, 2016). "A replication-competent oncolytic adenovirus lacking E1B suppresses the production of the pro-angiogenic factor VEGF-A in pancreatic cancer cells by disrupting the interaction between the transcription factor HIF-1α and the transcriptional co-activator p300." (PMID 26625205, 2016). "Be regulated through transcriptional regulation by HIF-1α, hypoxia induced Snail expression in pancreatic cancer cells." (PMID 26174737, 2015). "We have previously demonstrated that hypoxia-inducible factor-1α (HIF-1α) plays crucial roles in the pathogenesis and progression of pancreatic cancer." (PMID 25544770, 2015). "Further, we also validated two additional relevant proteins, HIF1α and PCNA, due to their well-established association with pancreatic cancer progression." (PMID 25929337, 2015). "The HIF-1α expression level was high in pancreatic cancer, and HIF-1α was related to clinical stage and lymph node metastasis." (PMID 25799412, 2015). "Further, the immunoblot analysis also showed that sanguinarine causes a decrease in hypoxia-inducible factor 1 alpha (HIF1α) and proliferating cell nuclear antigen (PCNA) in both BxPC-3 and MIA PaCa-2 pancreatic cancer cells." (PMID 25929337, 2015). "In this report, we proved that HIF-1α and SCF were prognostic factors in PDAC by examining the expression of SCF and HIF-1α in pancreatic cancer tissues and analyzing the clinical features and prognosis." (PMID 25799412, 2015). "In a further study on pancreatic cancer, insulin stimulates HIF-1α expression under hypoxic condition; in turn, insulin requires HIF-1α to promote glycolysis and cell proliferation." (PMID 25859407, 2015). "Bobarykina and colleagues showed that the PFKFB3 gene was expressed in gastric and pancreatic cancer cells and responded strongly to hypoxia via an HIF-1α dependent mechanism." (PMID 26337471, 2015). "Typically, Gem-resistant pancreatic cancer cells overexpress HIF-1α that mediates acquired drug tolerance and tumor progression." (PMID 25544770, 2015). "Using murine studies as well as molecular, and cellular studies in vitro, we demonstrate here that binding of RAGE to mutant KRAS is a direct, positive regulator of HIF1α-dependent hypoxia signaling in pancreatic tumor development." (PMID 25341034, 2014). "HIF-1α has been detected in both pancreatic cancer cells and surrounding stromal cells, in pancreatic cancer tissue specimens." (PMID 24782785, 2014). "Knock down of RAGE in vitro inhibits KRAS signaling, promotes HIF1α degradation, and increases hypoxia-induced pancreatic tumor cell death." (PMID 25341034, 2014).
pancreatic cancer (continued). "A recent study reported that HIF-1α had a higher expression in pancreatic cancer than that in the normal tissue, and that the level of HIF-1α protein expression is related to clinical stage and lymph node metastasis." (PMID 24662981, 2014). "Collectively, these findings suggest that RAGE expression is required for KRAS-mediated activation of HIF1α signaling and pancreatic cancer bioenergetics and growth in vivo." (PMID 25341034, 2014). "Suppression of HIF-1α using siRNA resulted in an enhanced efficacy of gemcitabine in the treatment of several pancreatic tumour cell lines." (PMID 25128202, 2014). "Our results provide a novel mechanistic link between NF-κB, KRAS, and HIF1α, three potent molecular pathways in the cellular response to hypoxia during pancreatic tumor development and suggest alternatives for preventive and therapeutic strategies." (PMID 25341034, 2014). "We now demonstrate that binding of RAGE to oncogenic KRAS facilitates hypoxia-inducible factor 1 (HIF1)α activation and promotes pancreatic tumor growth under hypoxic conditions." (PMID 25341034, 2014). "In contrast, a more recent study showed gemcitabine-induced activation of HIF-1α in normoxic pancreatic cancer cells." (PMID 25128202, 2014). "In the same way, the expression levels of CD133, CXCR4 and HIF-1α were also enhanced in the pancreatic cancer cell lines under hypoxia as compared with normoxic conditions and associated with an enhanced invasiveness of CD133+ pancreatic cancer cells." (PMID 23301832, 2013). "The expression level of hypoxia-inducible factor 1 alpha (HIF1α) was correlated with the presence of a fibrotic focus in pancreatic cancer tissue, suggesting desmoplasia provides a hypoxic condition within the tumor." (PMID 24198790, 2013). "This HIF1α-independent miR-210 induction affected the EMT of pancreatic cancer cells, suggesting an intriguing effect of tumor-stromal interaction." (PMID 24198790, 2013). "Recent studies have found that miR-210 expression is induced by HIF1α in pancreatic cancer cells and endothelial cells therefore providing a possible explanation as to why HIF1α activation can result in gene silencing." (PMID 23739951, 2013). "Recently, it has been demonstrated that the expression of CD133 was upregulated under hypoxia in a HIF-1α-dependent manner in pancreatic cancer cells, and knockdown of HIF-1α partially abrogated the elevated CD133 expression under hypoxia." (PMID 23840432, 2013). "Another study identified that HIF1α inhibitor PX-478 sensitized pancreatic cancer cells to radiation." (PMID 24198790, 2013). "A transcription factor hypoxia inducible factor-1α (HIF-1α), which mediates hypoxia responses, is overexpressed in many solid tumors, including pancreatic cancer." (PMID 23786654, 2013). "Meanwhile, overexpression of HIF-1α protein upregulated the expression of CX3CR1 in pancreatic cancer cells." (PMID 22952674, 2012). "The current study is the first to systematically investigate the in vitro and in vivo anti-tumor effects of KCN1 in pancreatic cancer cells in a HIF-1α-independent manner." (PMID 23028659, 2012). "Overexpression of HIF-1α significantly upregulated the expression of luciferase reporter gene under the control of the CX3CR1 promoter in pancreatic cancer cells." (PMID 22952674, 2012). "In pancreatic tumor samples, the expression of HIF-1α was correlated with upregulation of c-MET and its ligand hepatocyte growth factor (HGF) in both pancreatic cancer cells and stromal cells, and is linked with an increase in lymph node metastases." (PMID 24213498, 2012). "This study investigated the variation of hypoxia-inducible factor-1α(HIF-1α) expression and the apoptosis effect of hypoxia stimulated by cobalt chloride (CoCl2) in pancreatic cancer PC-2 cells." (PMID 22453051, 2012). "Twist is a transcriptional factor involved in the EMT of pancreatic cancer cells and HIF1α induces its expression." (PMID 22934011, 2012).